ARF6 (ARF GTPase 6)
Diseases named in the same sentence as ARF6 in open-access papers (continued):
Sharing a sentence is not in itself a finding about the gene and the disease.
atherosclerosis (4 papers, 2016 to 2025). A disease characterized by the build-up of fatty material and calcium deposition in the arterial wall resulting in partial or complete occlusion of the arterial lumen. "Because of the key role ROS plays in cardiovascular diseases, ARF6 could be a new potential therapeutic target for the treatment of atherosclerosis, restenosis after angioplasty and hypertension." (PMID 26824355, 2016). "We next examined if Arf6 heterozygosity results in blunted gene and protein expression of Arf6 in tissues involved in the development of atherosclerosis." (PMID 37163513, 2023). "This study supports the exploration of pharmacological Arf6 inhibition to attenuate the burden and severity of atherosclerosis." (PMID 37163513, 2023). "Many studies have shown that ARF6 plays a key role in atherosclerosis." (PMID 40176913, 2025). "Although we cannot differentiate between spontaneous plaque and oscillatory shear stress-induced plaque in the aorta, the attenuated size and severity of left carotid artery atheromas provide direct evidence that Arf6 reduction remarkably suppresses oscillatory shear stress-induced atherosclerosis." (PMID 37163513, 2023). "To test this hypothesis, we examined the burden and severity of atherosclerosis using Arf6 heterozygous (HET) and wildtype (WT) littermate control mice on the apolipoprotein E knockout (ApoE-/-) background." (PMID 37163513, 2023). "Taken together, the downstream genes of ARL4C, including ABCA1, ALDH1A3, ARF6, ENHO, FLNA, LRP6, OSBPL5, Snail2, and SOX2 play an important role in atherosclerosis." (PMID 40176913, 2025). "These ARF6-mediated events lead to activation of MMP14, a membrane-bound collagenase upregulated in atherosclerosis." (PMID 35680971, 2022).
gastric cancer (4 papers, 2015 to 2025). A primary or metastatic malignant neoplasm involving the stomach. "Together, these data point to the ability of Arf6/ERK-dependent mechanism that leads to increased EGF-induced EMT of gastric cancer cells by inhibiting Wnt5a transcriptional expression." (PMID 25779663, 2015). "ADP-ribosylation factor 6 (ARF6) is downstream of ARL4C and has been reported to play an important role in promoting gastric cancer EMT." (PMID 37237373, 2023). "MiRNAs can not only be used as biomarkers of gastric cancer, but also affect Akt and Akt, NF-κB, RAGE, ARF6, TCF4, STAT3 and other signaling pathways promote or inhibit the occurrence and development of gastric cancer." (PMID 35093110, 2022). "Taken together, we demonstrate for the first time a functional linkage between Arf6-ERK-Wnt5a signaling and induction of the EMT program in gastric cancer cell, which may shed light on new therapeutic targets for gastric cancer." (PMID 25779663, 2015). "Accordingly, we speculated that EGF/Arf6 signals might be able to repress Wnt5a transcription directly, thereby allowing EMT in gastric cancer cells." (PMID 25779663, 2015). "We also noticed that Arf6-T27N expression significantly suppressed ERK phosphoyrlation by EGF, suggesting that ERK might act as a downstream effector of Arf6 in mediating EGF-stimulated gastric cancer cell EMT." (PMID 25779663, 2015).
invasive breast carcinoma (4 papers, 2015 to 2023). A carcinoma that infiltrates the breast parenchyma. "Recent studies reported that GRB2 acts as an adaptor protein which plays a central role in the regulation of ARF1 and ARF6 activation in invasive breast cancer." (PMID 32595697, 2020).
Alzheimer disease (3 papers, 2015 to 2022). A progressive, neurodegenerative disease characterized by loss of function and death of nerve cells in several areas of the brain leading to loss of cognitive function such as memory and language. "As aberrant calcium homeostasis and lipid metabolism have been observed in Alzheimer's disease and FE65 is implicated in the pathogenesis of the disease, it is worthwhile to determine the roles of the ARF6-ARNO-FE65-ELMO1-DOCK180 multimeric complex in both physiological and pathological conditions." (PMID 36168805, 2022). "Arf6 expression increases through the hippocampus with the development of Alzheimer’s disease, being expressed mostly in the CA1 and CA2 regions in normal individuals but spreading through the CA3 and CA4 regions in individuals with pathologically diagnosed AD." (PMID 26170135, 2015). "ADAP1/Centaurin-α1 (CentA1) is an Arf6 GAP, which is known as a regulator dendritic differentiation and a potential mediator of Alzheimer’s disease (AD) pathogenesis." (PMID 33139322, 2021).
female infertility (3 papers, 2019 to 2024). Diminished or absent ability of a female to achieve conception. "Mutations in ARF6 and ARF8 caused male and female infertility." (PMID 31019434, 2019). "Because internalization of the LHR is regulated by Arf6, we constructed LHRN316S mice by CRISPR/Cas9 to further explore mechanisms of follicular development and novel treatment strategies for female infertility." (PMID 39150470, 2024). "The downregulation of ARF6 and ARF8 can result in female sterility." (PMID 33256588, 2020).
HIV-1 infection (3 papers, 2013 to 2025). The type species of lentivirus and the etiologic agent of acquired immunodeficiency syndrome (AIDS). "MDDCs transduced with shRNA targeting both ARHGAP24 and ARF6 (another small GTPase) showed increased susceptibility to HIV-1 infection." (PMID 40029073, 2025). "Furthermore, PIP2-associated plasma membrane changes driven by Arf6 are crucial for early HIV-1 infection, ensuring cell surface regeneration when the virus fuses with and enters permissive cells." (PMID 23575248, 2013).
liver cancer (3 papers, 2019 to 2022). An epithelial or non-epithelial malignant neoplasm that arises from the liver. "Kaplan-Meier survival curves showed that higher expressions of CD147, ARNO, and Rac1 mRNA were significantly associated with shorter overall survival (OS), whereas Arf6 mRNA expression was slightly associated with the survival of liver cancer patients." (PMID 31752956, 2019). "We showed that, by modulating the Rab5 and Rab22 co-activation, cell adhesion and junction formation, Arf6-driven CD147 endocytic recycling causes liver cancer cells to acquire migratory and invasive phenotypes." (PMID 31752956, 2019). "Also, ARF6 was linked to liver cancer through the regulation of the endocytic recycling of CD147, a tumor-related adhesive protein that promotes invasion of liver cancer cells." (PMID 32426352, 2020). "Although a study reported that CD147 depletion results in a ZO-1 increase in prostate cells, we found that Arf6-KD reduced CD147 recycling diminished ZO-1 in liver cancer cells, and Arf6 activation restored ZO-1 turnover." (PMID 31752956, 2019). "Our results revealed that Arf6-mediated CD147 endocytic recycling is required for the malignant phenotypes of liver cancer." (PMID 31752956, 2019). "We found that Arf6-mediated CD147 recycling promotes liver cancer cells adhering to key ECM-components." (PMID 31752956, 2019). "Arf6-KD yielded a significant reduction in cell migration and invasion capacity in all three liver cancer cell lines." (PMID 31752956, 2019). "Together, these data suggested that Arf6 expression promotes the endocytic recycling of CD147 in liver cancer cells, which largely occurs through concurrent activation of Rab5 and Rab22." (PMID 31752956, 2019). "Actually, in HGF-stimulated liver cancer cells, we found that Arf6-KD inhibited Rac1 activation and further over-expression of Arf6(Q67L) partially restored such inhibition." (PMID 31752956, 2019). "Here, we observed E-cadherin being significantly diminished or degraded in Arf6-KD liver cancer cells." (PMID 31752956, 2019). "We found that the endocytic recycling of CD147 in liver cancer cells was controlled by Arf6 through concurrent Rab5 and Rab22 activation." (PMID 31752956, 2019). "Since CD147-triggered ECM-degradation is a prerequisite for liver cancer invasion, MMPs secretion from Arf6-perturbed cells was examined." (PMID 31752956, 2019). "Further co-expression network analysis showed that CD147 highly expressed in liver cancer tissues correlates with Arf6, ARNO, and Rac1 expressions." (PMID 31752956, 2019). "We found that Arf6-KD reduced Rab5 and Rab22 activation in liver cancer cells, and such reductions were recovered by Arf6(wt), especially Arf6(Q67L) over-expression." (PMID 31752956, 2019). "We made three kinds of shRNA-lentivirus for human Arf6 gene silencing, and tested their silencing efficiency in commonly used liver cancer cell lines." (PMID 31752956, 2019). "The Arf6-driven signaling machinery provides excellent biomarkers or therapeutic targets for the prevention of liver cancer." (PMID 31752956, 2019). "Conversely, further over-expression of Arf6(Q67L) completely restored CD147 recycling in liver cancer cells." (PMID 31752956, 2019). "As expected, Arf6-KD markedly decreased the formation of polymerized actin stress fiber and lamellipodia numbers in liver cancer cells." (PMID 31752956, 2019). "Stable liver cancer cell lines with Arf6 silencing and over-expression were established." (PMID 31752956, 2019). "Disruption of Arf6-mediated CD147 trafficking markedly decreased the migration and invasion of liver cancer cells, while high expression of the Arf6-CD147 signaling components in HCC was closely correlated with poor clinical outcome of patients." (PMID 35978360, 2022). "In epithelial cells, Arf6 is an important regulator of intercellular adhesion and CD147 plays a significant role in adhesion modulation of liver cancer cells." (PMID 31752956, 2019).
liver cancer (continued). "To investigate the clinical significance of Arf6-mediated CD147 recycling, we determined the expression level of their signaling components in liver cancer patients." (PMID 31752956, 2019). "In summary, our study demonstrates that Arf6 is essential for the endocytic recycling of CD147 and its mediated malignant phenotypes in liver cancer cells." (PMID 31752956, 2019). "It was found that Arf6-KD reduced CD147 recycling which impaired the cell-cell contact and prevented the aggregation of liver cancer cells." (PMID 31752956, 2019). "When Arf6-KD cells were blocked with anti-CD147 pcAb, the Arf6(Q67L)-induced rescue effect disappeared, suggesting CD147 recycled to the cell-surface dictates the migration and invasion behaviors of liver cancer cells." (PMID 31752956, 2019). "Here, we found that Arf6 intervention slightly influenced CD147 uptake but markedly affected its recycling, which resulted in CD147 being highly present on the surface of liver cancer cells." (PMID 31752956, 2019). "However, the role of Arf6 in CD147 trafficking and its contribution to liver cancer progression remain unclear." (PMID 31752956, 2019). "GEPIA bioinformatics analysis showed that CD147, Rac1 and an Arf6-specific GEF ARNO exhibited higher transcription levels in liver cancer tissues than in matched normal liver tissues, whereas, the mRNA level of Arf6 and other Arf6-specific GEFs or GAPs (except ACAP3) tended to be no different." (PMID 31752956, 2019). "Although CD147 and Arf6 significant expression in liver cancer were already reported, we found for the first time that expression of the CD147-assocaited Arf6-ARNO-Rac1 signal axis in liver cancer tissues was significantly higher than in surrounding non-tumorous tissues." (PMID 31752956, 2019).
neuroblastoma (3 papers, 2013 to 2024). Neuroblastoma (NB) is the most common solid, extracranial childhood tumor. "The findings obtained from previous studies using the mouse neuroblastoma cell line N1E-115 will cast some light on the mechanisms underlying cytohesin–Arf6-dependent neurite outgrowth." (PMID 35563476, 2022). "Cocaine on binding to sigma-1 receptor (Sig-1R) has been shown to stimulate EV secretion from neuroblastoma cells by dissociating the Sig-1R from ARF6 (ADP-ribosylation factor 6) protein involved in EV trafficking." (PMID 38891019, 2024). "Proteins that were detected together with M1 receptors even in unstimulated neuroblastoma cells were caveolin-1 and -2, β-tubulin and ADP ribosylation factor 6 (ARF6)." (PMID 24705159, 2013). "Subsequent mass spectrometry-based proteomics of immunoprecipitates from neuroblastoma NSC-34 cells overexpressing human C9ORF72 identified cofilin, Arp2/3, coronin, Arf1, and Arf6 as novel C9ORF72 interactors." (PMID 35563476, 2022).
viral infection (3 papers, 2019 to 2024). "In addition, pharmacological inhibition of ARF6 with the small molecule NAV-2729 showed a dose-dependent reduction of viral infection." (PMID 37342971, 2023). "Arf6 plays various roles in virus infections, as it can be both required and abused for virus entry, replication, and secretion but also the support restriction of virus infection." (PMID 31060328, 2019).
allergic asthma (2 papers, 2015 to 2021). A asthma with a basis in a pathological type I hypersensitivity reaction. "Here, we found that OVA-induced allergic asthma was alleviated in mice with macrophages rendered phagocytosis deficient by conditional knockout (cKO) of Arf6 gene." (PMID 34423792, 2021). "OVA-induced allergic asthma and associated IL-1β production were alleviated in mice with small GTPase Arf6-deficient macrophages." (PMID 34423792, 2021). "Here, we found that macrophages are responsible for the cell-to-cell propagation of extracellular ASC specks through Arf6-dependent phagocytosis, leading to the exacerbation of allergic asthma." (PMID 34423792, 2021). "It will also be interesting to analyze the relapse rates of allergic asthma in patients treated with corticosteroids and Arf6 inhibitors, including SecinH3." (PMID 34423792, 2021). "Here, we demonstrated that Arf6 activation is required for the engulfment of extracellular ASC specks in airway macrophages, which leads to the exacerbation of allergic asthma." (PMID 34423792, 2021). "Furthermore, the upregulated genes (PDPK1, EZR, MYO6, CDC42BPA, OPHN1, ARF6 and WASL) identified in the present study that were enriched in the actin filament-based process require further study in order to determine whether they may be used as potential biomarkers of allergic asthma." (PMID 25633562, 2015).
Arthritis (2 papers, 2019 to 2021). Inflammation of a joint. "ARNO activates ARF6 to compromise vascular permeability in arthritis and other inflammatory conditions and it also triggers key effector mechanisms involved in cell migration." (PMID 35095899, 2021).
asthma (2 papers, 2021). "To elucidate the molecular mechanism of asthma exacerbation mediated by airway macrophages, we generated macrophage-selective Arf6-deficient mice (macrophage-Arf6 cKO) by mating Arf6fl/fl mice with LysM-Cre mice." (PMID 34423792, 2021). "To address this possibility, we examined whether the pharmacological inhibition of Arf6 activation suppresses asthma-like allergic inflammation in vivo." (PMID 34423792, 2021). "However, the amount of OVA-specific IgE, IL-5, and IL-13 in BALF obtained from macrophage-Arf6 cKO mice decreased compared with that obtained from WT mice, suggesting that macrophages exacerbate asthma-like allergic inflammation through Arf6." (PMID 34423792, 2021). "Arf6 is required for IL-1βproduction from airway macrophages in asthma-like allergic inflammation." (PMID 34423792, 2021). "Furthermore, pharmacological inhibition of the Arf6 guanine nucleotide exchange factor suppressed asthma-like allergic inflammation in OVA-challenged WT mice." (PMID 34423792, 2021). "Asthma exacerbation is alleviated in macrophage-Arf6 cKO mice." (PMID 34423792, 2021). "Collectively, the Arf6-dependent intercellular transmission of extracellular ASC specks contributes to the amplification of allergic inflammation and subsequent asthma exacerbation." (PMID 34423792, 2021). "Given the Arf6-dependent asthma-like allergic inflammation, we next examined IL-1β secretion in the OVA-challenged macrophage-Arf6 cKO mice." (PMID 34423792, 2021). "Collectively, we propose that Arf6 is required for the engulfment of extracellular ASC specks in airway macrophages and contributes to the exacerbation of asthma-like allergic inflammation." (PMID 34423792, 2021).
autism (2 papers, 2019 to 2024). Persistent deficits in social interaction and communication and interaction as well as a markedly restricted repertoire of activity and interest as well as repetitive patterns of behavior. "Through enzyme activity, IQSEC2 activates ARF6, a member of the Ras superfamily to facilitate downstream remodelling of actin cytoskeleton, a site of convergence with other ID and autism genes." (PMID 31439632, 2019). "Knockdown of Arf6 in mice results in enhanced seizure susceptibility, while dysregulation of ARF6 via IQSEC2 pathogenic variants are associated with epilepsy, intellectual disability, and autism." (PMID 38862622, 2024).
biliary atresia (2 papers, 2015 to 2020). A rare, biliary tract disease characterized by progressive obliterative cholangiopathy of the intra- and extrahepatic bile ducts, occurring in the embryonic/ perinatal period, leading to severe and persistent neonatal jaundice and acholic stool. "A recent study showed that ARF6 is involved in the EGFR pathway and is critical for proper bile duct formation, which suggests a non-superfluous role for USP6 in biliary atresia." (PMID 32848883, 2020).